S100A14 (S100 calcium binding protein A14)
Diseases named in the same sentence as S100A14 in open-access papers (continued):
Sharing a sentence is not in itself a finding about the gene and the disease.
gastric cancer (5 papers, 2017 to 2025). A primary or metastatic malignant neoplasm involving the stomach. "Decreased expression of S100A14 with its genetic variant may be associated with an undifferentiated phenotype and poor prognosis in gastric cancer." (PMID 29156846, 2017). "In parallel with these observations, S100A14 has been reported to regulate differentiation and migratory/invasive potential of gastric cancer cells." (PMID 31105881, 2019). "The expression of S100A14 in gastric carcinoma appears to be variable as compared to the normal control." (PMID 31105881, 2019). "In this study, we characterized the regulation of S100A14 expression between biological signatures and clinical pathological features in gastric cancer (GC)." (PMID 28726786, 2017). "Our findings demonstrate that S100A14 is a potential biomarker for predicting tumor metastasis and prognosis in gastric cancer." (PMID 28726786, 2017). "Furthermore, a recent study investigated the role of S100A14 in gastric cancer treatment outcomes by evaluating the combination of sintilimab (an anti-PD1 monoclonal antibody) and SOX therapy." (PMID 40806532, 2025). "Finally, we identified a gene set associated with the differentiation status of gastric cancer, including AGR3, CLDN3, CLDN4, FABP1, LGALS4, PHGR1, MYH14 and S100A14." (PMID 36729271, 2023). "Additionally, expression of S100A14 negatively regulated the migratory/invasive potential of gastric carcinoma cells in vitro and in vivo." (PMID 31105881, 2019). "Hence, these data demonstrated that S100A14 inhibited gastric cancer cell migration and invasion by modulating the store-operated Ca2+ influx." (PMID 28726786, 2017). "Furthermore, S100A14 has an important role in inhibiting the migration and invasion of gastric cancer cells by blocking the store-operated Ca2+ influx, leading to FAK activation and decreased MMP expression in GC cells." (PMID 28726786, 2017). "Secondly, S100A14 has been shown to promote differentiation of ESCC and gastric cancer cells." (PMID 31105881, 2019).
non-small cell lung carcinoma (5 papers, 2021 to 2024). A group of at least three distinct histological types of lung cancer, including non-small cell squamous cell carcinoma, adenocarcinoma, and large cell carcinoma. "CASC9 promotes the progression of non-small cell lung cancer through the miR-335-3p/S100A14 axis." (PMID 34101736, 2021). "In addition, a report also found that CASC9 could promote non-small cell lung cancer progression via miR-335-3p/S100A14 axis." (PMID 35419295, 2022).
thyroid cancer (5 papers, 2022 to 2025). "The evidence presented here suggests that ZHX2 inhibits the progression of thyroid cancer by blocking S100A14-mediated metastasis." (PMID 35151335, 2022). "The inhibition of S100A14 attenuated thyroid cancer cell metastasis induced by ZHX2 knockdown in cultured cells and in animal models." (PMID 36232466, 2022). "Nevertheless, our data demonstrated that ZHX2 inhibits thyroid cancer metastasis by repressing S100A14 expression at the transcriptional level." (PMID 35151335, 2022). "Based on bioinformatics analysis, we found that ZHX2 negatively correlated with S100A14 in thyroid cancer." (PMID 35151335, 2022). "Since ZHX2 is a well-known transcription factor, we examined S100A14 mRNA levels in thyroid cancer cell lines with ZHX2 manipulation." (PMID 35151335, 2022). "Inhibition of S100A14 attenuated the ZHX2 knockdown-induced enhanced metastasis of thyroid cancer cells both in vitro and in vivo." (PMID 35151335, 2022). "To further confirm that ZHX2 restrains thyroid cancer metastasis via S100A14, we performed lung metastasis assays in mouse models." (PMID 35151335, 2022). "More importantly, knockdown of S100A14 attenuated ZHX2 silencing-induced thyroid cancer cell migration both in vitro and in vivo." (PMID 35151335, 2022). "Here, we found that knockdown of S100A14 abolished ZHX2 silencing-induced cell migration both in vitro and in vivo, demonstrating that ZHX2 is involved in thyroid cancer metastasis through S100A14." (PMID 35151335, 2022). "More importantly, Kaplan–Meier curves revealed that high expression of S100A14 correlated with poor prognosis in thyroid cancer patients, suggesting that S100A14 is an oncogene of thyroid cancer." (PMID 35151335, 2022). "In conclusion, we identified S100A14 as a new target of ZHX2 and revealed that ZHX2 bound to the S100A14 promoter to repress its transcription, which in turn inhibited thyroid cancer metastasis." (PMID 35151335, 2022). "To verify whether the inhibition of thyroid cancer migration by ZHX2 was achieved by repressing S100A14, we performed the following experiments." (PMID 35151335, 2022). "Moreover, S100A14 was highly expressed in human thyroid cancer samples, and its expression negatively correlated with ZHX2 expression." (PMID 35151335, 2022). "Then, we aimed to determine the role of S100A14 in thyroid cancer." (PMID 35151335, 2022). "Above all, ZHX2 inhibits thyroid cancer migration via S100A14." (PMID 35151335, 2022). "Therefore, strategies aiming to manipulate ZHX2 and S100A14 might be helpful to treat thyroid cancer." (PMID 35151335, 2022). "Until now, the role of S100A14 in thyroid cancer metastasis has not been elucidated." (PMID 35151335, 2022).
bladder cancer (4 papers, 2019 to 2022). "Similar to breast, ovarian and bladder cancers, overexpression of S100A14 has been reported in hepatocellular carcinoma." (PMID 31105881, 2019).
breast tumors (4 papers, 2017 to 2025). "Additionally, S100A14 and TMPRSS4 were both hypomethylated and upregulated in breast tumors." (PMID 40943642, 2025).
colon cancer (4 papers, 2016 to 2025). "The S100A14 proteins were predominantly expressed on the membranes of colon cancer cells and its expression significantly correlated with several parameters." (PMID 39205741, 2024).
lung adenocarcinoma (4 papers, 2019 to 2025). A carcinoma that arises from the lung and is characterized by the presence of malignant glandular epithelial cells. "The S100A14 expression is associated with a subset of lung adenocarcinoma and has a strong correlation with the invasive and migratory nature of lung adenocarcinoma cells." (PMID 34239729, 2021). "In particular, S100A14 has been reported to be overexpressed in lung adenocarcinomas compared to normal control tissues and appears to predict poorer survival." (PMID 40869249, 2025). "Overexpression of S100A14 can lead to malignant progression and predict poor prognosis of lung adenocarcinoma." (PMID 38887981, 2024). "S100A14 has been reported to be over-expressed in lung adenocarcinomas as compared to the normal control tissues." (PMID 31105881, 2019). "Biological functions of S100A14 in lung adenocarcinoma have not been well investigated as compared to oral cancer or ESCC." (PMID 31105881, 2019).
hepatocellular carcinoma (3 papers, 2017 to 2019). A malignant tumor that arises from hepatocytes. "A decrease in cell proliferation and invasion was found with knock-down of S100A14 in hepatocellular carcinoma cells in vitro." (PMID 31105881, 2019). "Using immunohistochemistry on specimens of hepatocellular carcinoma (n=120) and their corresponding paratumor normal liver tissue (n=14), Zaho and co-workers found a higher S100A14 expression in carcinoma compared to the controls." (PMID 31105881, 2019). "Their claim was based on the wound healing assay and Matrigel transwell assay, which verified that S100A14 silencing suppressed cell migration and invasion while overexpression of S100A14 promoted migration and invasion of hepatocellular carcinoma cells." (PMID 28855549, 2017). "Although no molecular mechanisms have been suggested, these results indicate that S100A14 might promote hepatocellular carcinoma." (PMID 31105881, 2019).
nasopharyngeal carcinoma (3 papers, 2021 to 2022). A carcinoma arising from the nasopharyngeal epithelium. "In addition, a recent study proved that S100A14 suppresses the metastasis of nasopharyngeal carcinoma." (PMID 36114176, 2022).
oral cancer (3 papers, 2013 to 2022). "Notably, the data from a Norwegian team showed that the loss of S100A14 expression is associated with an invasive phenotype in oral cancer." (PMID 36114176, 2022). "Involvement of S100A14 in the regulation of oral cancer cell proliferation and invasion, by modulating expression of several molecules including p21, MMP1 and MMP9, was reported by our recent studies." (PMID 24086685, 2013). "Interaction between S100A14 and S100A16 proteins was verified by co-immunoprecipitation using the oral cancer derived CaLH3 cell-line." (PMID 24086685, 2013). "Considering the role of S100A14 in oral cancer cell proliferation and invasion and its ability to regulate the expression of S100A16, it can be speculated that the S100A14\S100A16 heterodimer might have a functional significance in human cancer cells." (PMID 24086685, 2013).
oral squamous cell carcinoma (2 papers, 2021 to 2022). "The binding of extracellular S100A14 with RAGE has been shown to control proliferation and apoptosis in esophageal cancer cells, and cell proliferation and invasion in oral squamous cell carcinoma." (PMID 36613714, 2022). "S100A16 in comparison to S100A14, in single cooperation in oral squamous cell carcinoma, indicated that S100A16 may serve the same purpose as S100A14." (PMID 36613714, 2022).
prostate carcinoma (2 papers, 2017 to 2022). A carcinoma that arises from epithelial cells of the prostate gland. "Depletion of FAT1 reversed the suppression of cell proliferation and EMT resulting from S100A14 overexpression in prostate cancer." (PMID 35965328, 2022). "We found three groups of genes in the EMT differentially expressed list: a) known EMT genes (e.g. CDH1, ZEB1, TGFB, CDH2, VIM, TIMP1), b) EMT genes previously unknown in prostate cancer (LSR, S100A14, DPYSL3) and c) novel EMT genes (including C1orf116)." (PMID 28651527, 2017). "We confirmed our discovery of unknown EMT genes in prostate cancer by testing expression of LSR, S100A14, and DPYSL3 in a PC3 prostate cancer cell line model of EMT." (PMID 28651527, 2017).
psoriasis (2 papers, 2022 to 2023). An autoimmune condition characterized by red, well-delineated plaques with silvery scales that are usually on the extensor surfaces and scalp. "S100a7a and S100a14, two genes associated with the severity psoriasis, showed decreased expression levels in the SS/PVA-treated group, which led to an improvement in the psoriatic condition." (PMID 36613589, 2022). "Sericin decreased the expression of the S100a7a and S100a14 genes, which are involved in the severity of psoriasis." (PMID 36613589, 2022).
adenoma (1 paper, 2025). A neoplasm arising from the epithelium. "However, the results highlighted in our study and our meta-analyses of existing datasets showed increased S100A14 expression in tumor lesions associated with the serrated pathway compared to tumors arising from the conventional adenoma–carcinoma sequence." (PMID 40806532, 2025). "We identified S100A14 as significantly overexpressed in sessile serrated lesions compared to low-grade adenomas, high-grade adenomas, and normal tissues." (PMID 40806532, 2025). "Collectively, proteomic and IHC results showed an increase in S100A14 in serrated lesions compared to adenomas and healthy diverticular margins." (PMID 40806532, 2025). "The same study identified S100A14 as one of the top hits overexpressed in SSL compared to adenomas and normal tissues." (PMID 40806532, 2025). "Due to its consistent differential expression between SSL and adenomas, S100A14 was selected as the main focus for further validation and characterization." (PMID 40806532, 2025). "Our proteomic study revealed a significantly higher distribution of S100A14 in serrated lesions compared to healthy tissues and conventional adenomas." (PMID 40806532, 2025).
colitis (1 paper, 2016). Inflammation of the colon. "Increased transcription of AMP transcripts, such as S100a8, S100a9, S100a14 and lactoferrin (Ltf) in the lumen of the gut during colitis suggests a required ability for commensal microbes to withstand antimicrobial activity during inflammation." (PMID 27003245, 2016). "Consistent with antimicrobial activity in the lumen of the gut during colitis, we observed significantly higher expression of the AMPs S100a8, S100a9, S100a14 and Ltf as well as Nos2 in colon contents." (PMID 27003245, 2016).
endometritis (1 paper, 2015). An acute or chronic, usually bacterial infectious process affecting the endometrium. "S100A14 has previously been reported as significantly increased in the endometrium from cows with endometritis." (PMID 26482908, 2015).
pancreatic ductal adenocarcinoma (1 paper, 2021). An infiltrating adenocarcinoma that arises from the epithelial cells of the pancreas. "Studies show that S100A14 protein is often overexpressed in pancreatic ductal adenocarcinoma (PDAC) cell lines and tissues." (PMID 34804125, 2021).
thyroid tumour (1 paper, 2022). "The expression of S100A14 negatively correlated with ZHX2 expression in human thyroid tumour specimens." (PMID 35151335, 2022). "Therefore, targeting ZHX2 and S100A14 signalling may be a useful strategy to inhibit thyroid tumour progression." (PMID 35151335, 2022).
triple-negative breast carcinoma (1 paper, 2024). An invasive breast carcinoma which is negative for expression of estrogen receptor (ER), progesterone receptor (PR), and human epidermal growth factor receptor 2 (HER2). "Authors identified the S100A14 as an independent predictor of triple-negative breast cancer prognosis, a subgroup that generally has unfavorable outcomes and does not respond to targeted therapy, becoming a potential new treatment target for this cancer." (PMID 39594999, 2024).
cancer (46 papers, 2011 to 2026). A tumor composed of atypical neoplastic, often pleomorphic cells that invade other tissues. "The interaction of RAGE and S100A14 is associated with increased cancer growth." (PMID 36613714, 2022). "Indeed, over-expression and knock-down of S100A14 in several cancer cell-lines was associated with concomitant up- and down-regulation of S100A16 protein but not mRNA." (PMID 24086685, 2013). "We next examined whether S100A16 over-expression is also associated with the concomitant change in the expression of S100A14 in cancer cell-lines." (PMID 24086685, 2013). "Taken together, these results show that S100A14 is overexpressed at each stage of the serrated pathway sequence, from serrated lesions to cancer, when compared to normal tissues." (PMID 40806532, 2025). "The heterogeneous expression profile of S100A14 across cancer types suggests a context-dependent, dual role for this protein, potentially acting as a tumor suppressor or promoter depending on the tissue microenvironment and molecular background." (PMID 40806532, 2025). "Intriguingly, S100A14 appears to exhibit both tumor-suppressive and tumor-promoting functions depending on the cellular context and cancer type." (PMID 39205741, 2024). "The known calcium-binding proteins (CALML5, S100A8, S100A14) modulate cancer therapeutics and survival." (PMID 38653992, 2024). "S100A2, S100A11, and S100A14 are three S100s with complex roles in cancer, as they have been described as either tumor suppressors or tumor promoters." (PMID 37627239, 2023). "S100A14 is highly expressed in some types of cancers, including ovarian, breast, and uterine cancers, and at low levels in the kidney, colon, and rectal cancers." (PMID 36613714, 2022). "Mounting evidence has shown that S100A14 is involved in many biological processes of cancer development, including cell proliferation, apoptosis, cell migration and cell differentiation." (PMID 35151335, 2022). "As a member of the S100 family, S100A14 (also known as breast cancer membrane protein 84) is a newly identified member of the S100 protein family and has recently gained significant attention in cancer research." (PMID 35151335, 2022). "Cancer and proliferation-related genes such as Wnt7b, S100a14, and Erbb2, were downregulated by thermal ablation in directly-treated tumors (A-T) 1 week after ablation, and to a lesser extent, 24 h after mechanical HIFU (M-T) compared to control (NTC)." (PMID 33441763, 2021). "S100A14, a novel member of the S100s, has been characterized by differentially expressed and functioned in various cancer types." (PMID 33815482, 2021). "Remarkably, we identified that the exosome-derived S100A14 plays a novel role in promoting cancer cell and macrophage migration and invasion and subsequent metastasis." (PMID 32483412, 2020). "S100A14 has been reported to be differentially expressed in various cancer types and has been suggested to be involved in key biological processes critical for cancerous phenotypes." (PMID 31105881, 2019). "Expression pattern of the S100A14 in different cancer types has a potential to be clinically useful as prognostic biomarker in the management of human cancers." (PMID 31105881, 2019). "Below we will summarize the functional roles and related molecular pathways of S100A14 in major cancer types." (PMID 31105881, 2019). "Compared to the normal counterparts, the expression of S100A14 mRNA/protein has been found to be deregulated in several cancer types, indicating a functional link between S100A14 and malignancies." (PMID 31105881, 2019). "Compared to the normal counterparts, S100A14 mRNA and protein levels have been found to be deregulated in several cancer types, indicating a functional link between S100A14 and malignancies." (PMID 31105881, 2019). "Below we describe the expression pattern of S100A14 in some of the cancer forms where S100A14 has been well investigated." (PMID 31105881, 2019).